IL17A (interleukin 17A)
Diseases named in the same sentence as IL17A in open-access papers (continued):
Sharing a sentence is not in itself a finding about the gene and the disease.
tumor (continued). "Furthermore, mice transfused with CD4+ T cells plus TCN and IL‐17A neutralizing antibody, showed decreased the proliferation of GC tumor cells as well as IL‐17A production, compared to mice transfused with CD4+ T cells plus TCN and control IgG." (PMID 34185422, 2021). "Deletion of Il17a or Il17f reduces tumor development in an APC-driven mouse model of CRC." (PMID 34489941, 2021). "Either CD4+ Th1 or Th17 cells promote CD8+ cells activation, and a lower infiltration of IL-17A-expressing cells could indicate a diminished anti-tumor response." (PMID 34944746, 2021). "Wang and colleagues revealed IL17A promoted tumor progression via STAT3/NF-κB/Notch1 pathway." (PMID 34122408, 2021). "As for no IL‐17A expression in neutrophils in co‐culture systems above, the data above indicate that IL‐17A from tumor‐associated neutrophil‐polarized IL‐17A‐producing Th subsets contributes to the progression of GC tumors in vivo." (PMID 34185422, 2021). "The results showed that the anti-IL17A mAb could inhibit N2-phenotype induction in neutrophils mediated by high-dose tumor culture supernatant, while the anti-IFN-γ mAb could induce the transformation of neutrophils from the N1 phenotype to the N2 phenotype." (PMID 34721375, 2021). "Moreover, we also indicated that T lymphocyte infiltration in the tumor microenvironment is critical for IL-17A-IL-17RA/IL-17RC-modulated LUAD progression." (PMID 33802737, 2021). "Given the tumoral neutrophils induced IL‐17A‐producing Th subset polarization surpasses non‐tumor tissue neutrophils, we thus presumed that tumors might have effects on this process." (PMID 34185422, 2021). "Indeed, to secrete IL-17A and recruit myeloid cells into the tumor in a mouse ovarian cancer model, CD4 T cells needs the expression of TNFR1." (PMID 33498483, 2021). "Notably, there was a reduction of F4/80+ tumor-associated macrophages (TAM) and especially in F4/80+ CD206+ cells in tumors from IL17A−/− mice and with a greater extent in tumors from WT mice treated with the anti-IL17A mAb." (PMID 33802061, 2021). "Presently, there are so many areas unknown about the regulatory mechanism and potential role of these IL‐17A‐producing Th subsets in GC tumor immunopathology." (PMID 34185422, 2021). "Among all the members, IL17A is the most controversial in regulating tumor immunity." (PMID 33802061, 2021). "One such study involving mice bearing genetically engineered Kras G12D-/IL-17A-expressing lung tumors, clearly demonstrated dependence of both tumor progression and resistance to PD-1 targeted immunotherapy on neutrophil recruitment that was driven by tumor-derived IL–17A." (PMID 34168563, 2021). "Herein, we found that neonatal inoculation of ApcMin/+ mice with F. nucleatum strain Fn7-1 circumvents technical barriers preventing its intestinal colonization, drives colonic Il17a expression prior to tumor formation, and potentiates intestinal tumorigenesis." (PMID 34781821, 2021). "In the mouse model, IL-17A enhanced tumor progression and fibrosis." (PMID 32488650, 2021). "We found that tumor-infiltrating γδT cells in the high-dose treatment group can only exert immunosuppressive effects in the presence of neutrophils, and this effect can be antagonized by IL17A mAb." (PMID 34721375, 2021). "We suggest that IL-17A rs8193036 SNP might affect LUAD tumor progression and its clinical course in patients harboring the WT EGFR and MT KRAS." (PMID 33802737, 2021). "A tumor-bearing mouse model showed tumor-infiltrating Treg cells can be converted from IL17A+FoxP3neg cells fostered by TGFβ and PGE2, which is consistent with our results about two Treg states and development pathways of naïve CD4+ T cell to TH17-like subsets and then Treg subsets in AML patients." (PMID 33648605, 2021).
tumor (continued). "To further demonstrate that neutrophils differ depending on the cytokines secreted in the tumor, we extracted culture supernatants from tumor tissues after treatment with different doses for induction of naive neutrophils, and an anti-IL17A mAb and anti-IFN-γ mAb were given as appropriate." (PMID 34721375, 2021). "Having demonstrated that AdIL-17A-transduced 4T1 tumor cells potently promote the expansion of MDSCs in tumor-bearing mice, we wondered whether tumor-derived IL-17A could alter the quality of MDSCs." (PMID 32770025, 2020). "Also, IL-17a-/--attenuated tumor growth was recovered in PM2.5-exposed mice injected with recombinant mouse IL-17a, accompanied with significantly restored lung metastasis." (PMID 32554855, 2020). "Moreover, IL-17A has been shown to increase tumor angiogenesis and thereby promote tumor progression, including CRC progression." (PMID 32492770, 2020). "Moreover, IL-17A is known to stimulate tumor cell proliferation and metastasis in non-small-cell lung cancer and breast cancer." (PMID 32756356, 2020). "To assess how IL-17A-induced cytokine responses may influence tumor progression, we inoculated Ad-transduced 4T1 tumor cells into syngeneic BALB/c mice via orthotopic injection into the mammary fat pad." (PMID 32770025, 2020). "In addition, the in vivo subcutaneous tumor model confirmed that A549-drived tumor growth was further accelerated by PM2.5, which was clearly abolished by the loss of IL-17a, accompanied with significantly reduced lung metastasis." (PMID 32554855, 2020). "Additional studies are warranted to investigate whether tumor-derived IL-17A may also stimulate production of these cytokines and growth factors from tumor resident stromal cells and/or tumor resident macrophages through a paracrine pathway." (PMID 32770025, 2020). "Furthermore, in tumor tissue supernatants from Rag2−/− mice, IFNγ and IL-17A were significantly increased, while IL-10 was significantly decreased." (PMID 33042110, 2020). "IL-17A-producing γδ T cells (Tγδ17 cells) are the primary pro-tumor γδ T cell subset." (PMID 33255339, 2020). "Therefore, it is possible that the molecular relationships between RORγt and IL-17A, IL-23 and IL-1β seen on lymphocytes cannot be extrapolated to tumor cells." (PMID 32139737, 2020). "The role of IL-17A-producing γδT cells in tumor development is controversial and could be tumor model-dependent." (PMID 33178187, 2020). "Given a known function of IL-17A in promoting cellular immune responses, we hypothesized that the intense IL-17A+ cellular infiltration found in TNBC patients might be triggered and/or attributed by tumor-derived IL-17A production." (PMID 32770025, 2020). "IL‐17A derived from γδT17 cells plays an important role in chemotherapy‐induced anticancer immune responses by preceding the accumulation of Tc1 CTLs within the tumor bed." (PMID 31903715, 2020). "Furthermore, IL‐17A supplementation significantly enhanced anti‐tumor responses in young mice, prolonging the mean survival from 33.60 to 38.50 days." (PMID 31903715, 2020). "However, IL-17A plays a dual role in promoting both tumor growth and antitumor immunity in skin cancer." (PMID 32765487, 2020). "In addition to IL-17A production, IL-4 expression has been shown to inhibit the anti-tumor response of Vγ9+Vδ2+ T cells via the promotion of IL-10-producing Vδ1+ T cell growth." (PMID 33255339, 2020). "Therefore, to further examine the direct role of these cytokines in the tumor microenvironment, recombinant IFNγ or IL-17A were injected peritumoraly three times a week for up to 4 weeks." (PMID 33042110, 2020). "Among them, the expression levels of IL-17a and IL-17f are related to tumor angiogenesis." (PMID 32522267, 2020). "Thus, IL-17A produced by Th17 and γδ T cells establishes an immune system to tumor crosstalk via the IL-17A receptor on PanIN cells." (PMID 32210079, 2020).
tumor (continued). "On the other hand, IL-17A also recruits mouse innate immune cells like neutrophils and immature myeloid cells within the tumor, supporting the development of an immunosuppressive microenvironment, eventually favoring tumor growth." (PMID 33244315, 2020). "IL-17A can favor tumor growth either in a direct or in indirect manner." (PMID 33244315, 2020). "IL-17A+TNF+ TCRγδCD8− T cells might thus constitute a particularly detrimental cell population in the tumor and counteract the potential positive effect of Treg depletion on CD8αβ T cells." (PMID 32185408, 2020). "The expression of IL-17a mRNA increases with the increase of tumor invasion and pathological stage." (PMID 32522267, 2020). "While a skewed MAIT cell response toward IL-17 production has been proposed to potentially promote tumor progression, IL17A transcripts were undetectable in most MAIT cells within the datasets analyzed, possibly reflecting their relatively low baseline abundance." (PMID 32849590, 2020). "Additionally, results by in vivo tumor metastasis confirmed that IL-17a knockout inhibited metastasis in PM2.5-challenged mice." (PMID 32554855, 2020). "Since the Th17 cell subset is a major cellular source of IL-17A and IL-17F, we hypothesized that the downregulation of these two cytokines was related to the number of Th17 cells in tumor tissue." (PMID 33102239, 2020). "Furthermore, the changes in CD4+ and CD8+ T cell cytokines produced in the tumor microenvironment after G-CSFR−/− cell injection led us to test the ability of IFNγ or IL-17A alone to inhibit tumor growth." (PMID 33042110, 2020). "Upon activation, we observed altered transcription of KITLG, TGFB1, IFNG, SPP1, IL17A and PDCD1, whose associated functions and expression pattern marked and improved OS of BrC patients, supporting that MCs contribute with a tumor stroma with anti-tumoral functions in BrC." (PMID 32722549, 2020). "IL-17A has been shown to promote anti-tumor T cell response in murine models and human tumors." (PMID 33178187, 2020). "In addition, IL-17a deletion markedly abolished the role of PM2.5 in promoting tumor growth and metastasis in mouse models." (PMID 32554855, 2020). "As in the tumor tissues, IFNγ, IL-10, IL-17A, and IL-4 were measured and similar to tumor tissues, in vitro culture of T cells were found to have significantly increased levels of IFNγ and IL-17A, with G-CSFR−/− CD4+ T cells, while IL-10 and IL-4 levels were decreased compared to WT." (PMID 33042110, 2020). "We report that the acquisition of tumor aggressiveness in patients is dependent on close associations prevailing between NOS2 and IL-10 synthesis and between IL-17A, TGF-β, and MMP-9 and identifies IL-17A as a possible key predictor of LSCC aggressiveness and resistance to therapy." (PMID 31885577, 2019). "Cisplatin treatment could restore the splenic immunophenotype downregulating CD44+, IL-17A+ MDSCs presumably because of the smaller tumor burden, on the other hand MDSCs are also sensitive to low dose chemotherapy due to their high proliferative potential." (PMID 31881770, 2019). "Specifically, IL-17A from γδ T cells has been shown to induce angiogenesis within the tumor microenvironment (TME), and increase recruitment of immunosuppressive cell types like myeloid-derived suppressor cells (MDSCs), neutrophils, and tumor associated macrophages." (PMID 31849992, 2019). "Considering that tumour metastasis is often associated with poor prognosis and high mortality among GBM patients, our study is clinically relevant and IL‐17A signalling could be a novel target for GBM therapy, especially GBM metastasis." (PMID 30353649, 2019). "Afterwards, the expression levels of 12 cytokines including IL-1a, IL-1b, IL-2, IL-4, IL-6, IL-8, IL-10, IL-12, IL-17A, TNFα, IFNγ and GM-CSF in secretome of hWJ-MSCs alone as well as in supernatant of tumor cells before and after treatment with hWJ-MSCs secretome were evaluated." (PMID 31857970, 2019).
tumor (continued). "In addition, it is most important to clarify and determine the potential functions of IL‐17A in the tumour tissues derived from GBM patients." (PMID 30353649, 2019). "In addition, some scientists have found that IL-17A can promote the formation of tumor blood vessels, thereby contributing to the proliferation and invasion of tumor cells." (PMID 31832112, 2019). "In addition, high baseline serum IL-17A concentrations have been associated with shorter progression-free survival in CRC patients, and tumor dissemination in small cell lung cancer patients." (PMID 31387598, 2019). "Published data indicate that IL-6 or IL-17A acts as a pro-tumor factor in MCL or DLBCL." (PMID 30755239, 2019). "Furthermore, we compared the levels of IL-17A in PB and tumor tissues of OC patients and found the levels of IL-17A produced by γδ T cells in OC tissues were higher than that in PBof OC patients (P < 0.001)." (PMID 31064389, 2019). "Given the apparent association of Th17 cells and IL-17A with some types of IRAEs, co-administration of IL-17A/IL17AR MAbs together with ICI-targeted MAbs may not only enhance anti-tumor immunity, but also attenuate or prevent the development of IRAEs." (PMID 31616428, 2019). "Similarly, mice treated with antibiotics to induce a depleted commensal microbiota displayed reduced tumor size and expression of IL-23 and IL-17A." (PMID 30894857, 2019). "IL17A promotes myeloid cell recruitment, which can suppress tumor immunity." (PMID 31921642, 2019). "IL-17A has also been shown to enhance CCL20 production in various tumor cells." (PMID 31387598, 2019). "Interestingly, the levels of IFN-γ and IL-17A secreted by tumor-infiltrating γδ T cells revealed similar results." (PMID 31064389, 2019). "Furthermore, ruxolitinib elevated numbers of tumor infiltrating CD4+IL17A+ Th17 and CD4+Foxp3+ regulatory T cells." (PMID 31407334, 2019). "A higher percentage of IL‐17A+ cells was observed in PVTT than in tumour tissues." (PMID 29689643, 2018). "To assess the efficacy of IL‐17A targeting therapeutics in preventing HCC progression, we administered secukinumab, an anti‐human IL‐17A monoclonal antibody approved for several inflammatory disorders, to treat an orthotopic implantation tumour model in combination with sorafenib." (PMID 29689643, 2018). "Finally, we found a decreased methylation of the IL17A locus in CD4+ T cells in the tumour compared to PBMCs (p < 0.01)." (PMID 30075815, 2018). "However, some studies have revealed that IL-17A inhibits the development of tumours and there is only one survey that analyses the IL-17A impact on the PA growth." (PMID 29955610, 2018). "Furthermore, consistent with our previous results, IL-17A was found to be significantly increased within the CD4+Foxp3− tumor infiltrated lymphocytes, suggesting that these ex-Foxp3 TH17 cells maintain their ability to produce pro-inflammatory cytokine." (PMID 30413714, 2018). "Interestingly, ∼26% of mice intranasally treated with L. lactis-IL-17A and challenged with TC-1 cells remained tumor free over the experiment, in contrast to control mice treated with the wild type strain of L. lactis which developed 100% of aggressive tumors." (PMID 30728820, 2018). "In this study, we revealed that epidermal IGF-1 production, which is required for efficient wound healing, could be downregulated by IL-17A after skin injury." (PMID 29483920, 2018). "rIL-17A notably enhanced the in vitro production of IL-1β and IL-23 by primary keratinocytes at both the mRNA and protein levels, suggesting that IL-17A is an important factor to enhance epidermal IL1/23 production in the epidermis around wounds after skin injury." (PMID 29483920, 2018). "In addition, to our knowledge this is the first demonstration for tumor-derived ADM to induce mast cell degranulation in GC microenvironment, which exerts protumorigenic roles by facilitating tumor progression via releasing pro-inflammatory IL-17A." (PMID 30305610, 2018).
tumor (continued). "In addition, the median size of the ∼74% tumor-bearing mice treated with recombinant L. lactis-IL-17A, was significantly lower than mice treated with L. lactis-wt." (PMID 30728820, 2018). "Moreover, cordycepin significantly suppressed IL-17A levels in the culture supernatant of tumor-draining lymph node cells." (PMID 29212184, 2017). "The main producing cytokine of Th17, recombinant IL-17A administration could reverse the anti-tumor effects of SBE." (PMID 28086772, 2017). "In addition to natural (n)Treg and induced (i)Treg cells that develop from naive precursors, suppressive IL-17A+Foxp3+ and ex-Th17 Foxp3+ cells are converted from IL-17A+Foxp3neg cells in tumour-bearing mice." (PMID 28290453, 2017). "Consequently, we suggest that IL-17A induced by intravesical chemotherapy plays a role in enhancing anti-tumor immunity towards NMIBC." (PMID 28406993, 2017). "Combined IL-17A/PDL1 Ab injection significantly increased the survival rate in the current study, and IL-17A Ab injection could reduce the dose of PDL1 Ab in tumor-bearing mice." (PMID 27935862, 2017). "We next investigated whether intratumoral IL-17A was associated with clinicopathological features such as primary tumor (T), lymph node status (N), TNM stage, tumor differentiation of cancer patients." (PMID 29029520, 2017). "Because IL-17A Ab could decrease PDL1 expression in tumor tissues, we decided to treat the tumor-bearing mice with combined IL-17A and PDL1 Abs." (PMID 27935862, 2017). "We previously reported that JC-001 down-regulates systemic Th17-mediated immunity in both Hepa 1-6 and LLC1 immunocompetent tumor models and up-regulates IL-10 secretion and down-regulates IL-17A in conditioned medium from co-cultured tumor cells and splenocytes." (PMID 28399860, 2017). "Next, we increased the dose of IL-17A Ab to check whether targeting of IL-17A increased the survival time of tumor-bearing mice." (PMID 27935862, 2017). "Interestingly, a recent study showed that blocking of IL-17A in an adenomatous polyposis coli (APC)-mediated colon carcinogenesis model enhanced tumor sensitivity to the anticancer agent 5-fluorouracil." (PMID 28492497, 2017). "IL-17A shows its bidirectional functions both in pro-tumor and anti-tumor effect." (PMID 29029520, 2017). "Accordingly, in the murine experimental model of colitis-associated cancer (CAC), both the tumor multiplicity and growth were diminished in the absence of IL-17A, IL-6, IL-11 or TNF-α." (PMID 28881574, 2017). "The strong effect of the anti-IL-17A Ab on PDL1 expression in murine tumor cells, macrophages, and MDSCs prompted us to further investigate whether targeting of IL-17A could transform the tumor microenvironment." (PMID 27935862, 2017). "TH17 cell-derived IL-17A favors tumor progression and neoangiogenesis." (PMID 27832300, 2017). "Besides that, IL-17A has been considered as a potent activator of pro-tumor innate immunity by regulation and suppression of T lymphocyte function in the tumor microenvironment." (PMID 28609459, 2017). "IL-17A promotes tumor cell survival and invasiveness and inhibits the antitumor immune response." (PMID 27935862, 2017). "We hypothesize that IL-17A promotes excretion of G-CSF by stromal cells and the subsequent induction of neutrophils leads to anti-tumor activity through Fas and/or TRAIL apoptotic pathways." (PMID 28406993, 2017). "Because targeting of IL-17A lowered PDL1 expression in tumor tissues and promoted the T cell response, especially of CD8+ T cells, in tumor-bearing mice, we next sought to determine whether antitumor immunity could be established by anti-IL-17A injection." (PMID 27935862, 2017). "However, the studies included in these meta-analyses reported the different sources of IL-17A involving tumor tissue, peripheral blood or peritoneal lavage and different detecting methods such as Flow Cytometry, ELISA, IHC and RT-PCR." (PMID 29029520, 2017). "IL-17A is produced by Th17 cells and promotes a pro-tumor environment." (PMID 28399860, 2017).